ATR (ATR checkpoint kinase)
Diseases named in the same sentence as ATR in open-access papers (continued):
Sharing a sentence is not in itself a finding about the gene and the disease.
cancer (continued). "Comprehensive DNA sequencing efforts identified ~4,000 cancer-associated mutations in ATM/ATR; however, their cancer implications remain largely unknown." (PMID 33742106, 2021). "We find that the number of mutated ATM/ATR residues varies widely from one cancer type to another." (PMID 33742106, 2021). "Moreover, in cancer cells, PD-L1 is associated with the activation of DNA damage repair kinases such as ATR and ATM23." (PMID 34158547, 2021). "We combine a systems pharmacology approach with an agent-based modelling approach to simulate LoVo cells subjected to AZD6738, an ATR (ataxia–telangiectasia-mutated and rad3-related kinase) inhibiting anti-cancer drug that can hinder tumour proliferation by targeting cellular DNA damage responses." (PMID 34459993, 2021). "ATM and ATR are conserved regulators of the DNA damage response linked to cancer." (PMID 33742106, 2021). "ATR inhibition is lethal with numerous cancer-associated changes, including oncogenic stress (oncogenic RAS mutations, MYC and G1/S-specific cyclin-E1 (CCNE1) overexpression), deficiencies in DNA repair (TTP53, BRCA1/2, partner and localizer of BRCA2 (PALB2) and ATM loss) and other defects." (PMID 32316968, 2020). "Despite olaparib and ATR inhibitors demonstrating various degrees of monotherapy efficacy in ATM-deficient cancers, our work highlights the importance of exploring their use in combination through the potential to optimise lower doses and shorter treatment periods due to synergistic activity." (PMID 32444694, 2020). "In addition, we outlined the therapeutic prospects of current ATR DDR inhibitors for HPV-associated cancers combined with traditional therapies." (PMID 32585979, 2020). "Moreover, even PARPi-resistant BRCA1-deficient cancer cells are sensitive to ATR inhibition, in part due to the role of ATR in supporting BRCA1-independent loading of RAD51." (PMID 32015826, 2020). "In the following paragraphs, we will detail the activation pathway, and compare the unique features of mouse models with null or KD mutations of ATM, ATR and DNA-PKcs and attempt to summarize their common features and their implications in human disease and cancer therapy." (PMID 32015826, 2020). "We previously showed that depletion of endogenous A3A and A3B from certain cancer cell lines reduced their susceptibility to ATR inhibition, suggesting that both A3A and A3B may contribute to the vulnerability of tumors." (PMID 32532990, 2020). "Notably, CDK1 inhibition significantly reduced the levels of genomic instability, underlining that premature entry induced by ATR inhibition drives genomic instability in PARP inhibitor‐treated BRCA2‐depleted cancer cells." (PMID 31529615, 2019). "Together, these results suggest that the combination of a PARP inhibitor with an ATR inhibitor may have significance for the treatment of patients with ATM-deficient cancers." (PMID 31481733, 2019). "Ataxia Telangiectasia and Rad3 related protein (ATR) is a central mediator of the response to DNA damage that may cause the quiescent resistance of cancer initiating cells to genotoxic radiotherapy." (PMID 29685176, 2018). "Given the current pharmaceutical interest in the development of ATR inhibitors for cancer therapy, we pre-clinically tested whether ATR inhibition could be selectively toxic in PTEN-deficient cells." (PMID 29396668, 2018).
cancer (continued). "Potentiation of DNA replication stress to toxic levels by inhibiting the ATR kinase is a strategy being used to target the chronic DNA replication stress phenotype of cancer cells, and this would be expected to make ATR-deficient cancer cells even more reliant on MiDAS for survival." (PMID 29695617, 2018). "Discovery of more biomarkers, specifically those also involved in the ATR pathway, may be particularly effective as a diagnostic method for detecting levels of replication stress in early stages of cancer development." (PMID 28587102, 2017). "Interestingly, the combination of ATR inhibitor with Olaparib synergistically sensitizes NEIL3 deficient cancer cells, suggesting that blocking the ATR-mediated DNA damage response synergizes the cytotoxicity of PARP1 inhibitor." (PMID 29348879, 2017). "We propose the hypothesis that if cancer cells rely on ATR signaling for DNA repair, they are susceptible to genotoxic agents at least due in part to defects in DNA repair functions." (PMID 26657501, 2016). "As cancer cells deficient in ATR or DSB repair are sensitive to inhibitors of PARP1, we hypothesized that inhibition of ATR and PARP1 would result in more sensitization to the DSB inducing agent, irinotecan." (PMID 26257651, 2015). "Although the degree of INPP4B loss that is needed for cancer cells to down-modulate ATR and BRCA1 levels and to acquire sensitivity towards PARP inhibitors still needs to be determined, we found that INPP4B loss greater than 50% in MEFs resulted in reduced levels of BRCA1, ATM and ATR proteins." (PMID 25868852, 2015). "Taken together, this creates a complex picture where either abnormal low expression, or high expression, of ATR, Chk1, or Wee1 in cancer cells may potentially cause increased sensitivity to inhibitors of these checkpoint kinases." (PMID 25774168, 2015). "Additionally, we tested select mutations in this ATR region identified through cancer genome sequencing efforts." (PMID 24901225, 2014). "The five most significant BioCarta pathways were first multivalent nuclear factor, FAS signaling pathway (CD95), p38 MAPK signaling pathway, control of skeletal myogenesis by HDAC and calcium/calmodulin-dependent kinase (CaMK), role of BRCA1, BRCA2, and ATR in cancer susceptibility." (PMID 21836821, 2011). "Thus, beyond ATR signaling, disruption of TopBP1 compartmentalization by quinacrine may inhibit additional TopBP1-associated functions that determine the capacity of cancer cells to process DNA lesions in coordination with cell cycle progression." (PMID 41190242, 2025). "Importantly, ATR inhibition abolishes the restored RAD51 foci and the loading of RAD51 to replication forks in BRCA1-deficient, PARPi-resistant cancer cells, supporting the idea that ATR inhibition disrupts a common RAD51-mediated mechanism driving PARPi resistance." (PMID 39007266, 2024). "Thus, ATR mutation are the most common in EC compared to the other cancer type." (PMID 38669256, 2024). "Therefore, SLFN11 may serve as a diagnostic marker, as cancers with low SLFN11 expression are expected to be highly vulnerable to pharmacological inhibition of ATR pathway components when exposed to DDAs." (PMID 38791884, 2024). "In addition, ATR inhibition has been shown to cause depletion of HR factors in cancer cell lines." (PMID 36755963, 2023).
cancer (continued). "In addition, cis-ATR could be a diagnostic marker for prognosis and efficacy in the treatment of cancer." (PMID 37511442, 2023). "Thus, inhibition of ATR can theoretically eliminate ARID1A-deficient cancer cells." (PMID 36123603, 2022). "Likewise, ATR blockade further disrupted HR repair pathway in BRCA‐deficient cancer cells." (PMID 34977872, 2021). "Thus, the combination of PARP and ATR inhibitors could be beneficial in a number of ATM-deficient cancers, including lung, prostate and pancreatic." (PMID 32183301, 2020). "Also, cis-ATR might serve as a diagnostic marker of prognosis and treatment efficacy in cancer management." (PMID 32426354, 2020). "For example, the gene sets G2/M checkpoint, activation of ATR in response to replication stress, and mitotic spindle checkpoint indicate alterations in pathways associated with cell-cycle-arrest in response to DNA damage, which are central alterations in cancer." (PMID 33396205, 2020). "Indeed, ATR inhibition preferentially targets HR-deficient cancer cells." (PMID 27472395, 2016). "Here, we investigated the roles of RAD9-HUS1-RAD1 interacting nuclear orphan 1 (RHNO1) in cancer progression and its involvement in maintaining ATR/Chk1 signaling during the DNA replication stress response." (PMID 42239230, 2026). "Elevated DNA replication stress is a common feature of cancer cells, rendering them dependent on ATR/Chk1 signaling, which controls the DNA replication stress checkpoint, for survival." (PMID 42239230, 2026). "Potential synergy in cancer cell cytotoxicity has been studied by combining ATR inhibitors AZD6738 or M6620 with a wide arrange of chemotherapeutic agents, from cisplatin and carboplatin to topotecan and gemcitabine." (PMID 40422251, 2025). "The efforts culminated in the identification of a compound endowed with striking ATR inhibitory activity and remarkable cell growth inhibitory effects against ATM-deficient cancer lines." (PMID 40256842, 2025). "Simultaneous inhibition of ATM and ATR has been shown to induce cancer cell death through synthetic lethality in preclinical models." (PMID 40875525, 2025). "ATR inhibitors render tumor cells sensitive to PARP inhibitors and sensitize BRCA-deficient cancer cells with acquired resistance to PARP inhibitors." (PMID 41440239, 2025). "In recent studies, ATR inhibition (ATRi) has been shown to resensitize PARPi-resistant cancer cells." (PMID 40739089, 2025). "Research indicates that inhibition of type I and II PRMTs can reduce phosphorylation and overall ATR in cancer cells, presenting new approaches for cancer therapy." (PMID 39964832, 2025). "We propose the underlying mechanism that RBM17 promotes CHEK1 protein expression in the ATM/ATR pathway, triggering the development of chemoresistance in cancer cells." (PMID 40243905, 2025). "Overall, ATR inhibitors are transforming cancer therapy by targeting DNA repair vulnerabilities and boosting the effectiveness of genotoxic treatments." (PMID 40256842, 2025). "ATR/Chk1 signaling, hyperactive in cancer cells as a result from replication stress and uncontrolled proliferation, offers a good opportunity for synthetic lethality." (PMID 40422251, 2025). "In this study we review the ATM/Chk2 and ATR/Chk1 axes in cancer and the new drugs developed to inhibit these proteins, which are being tested in different phases of preclinical experimentation or clinical trials." (PMID 40422251, 2025). "In multiple cancer cell models, suppression of mTORC1 activity by ATR inhibition or knockdown was rescued by exogenous cholesterol or lanosterol." (PMID 40514450, 2025).
cancer (continued). "Remarkably, a similar observation was made in other types of cancer: high AEP expression levels and low ATR levels correlated with poor prognosis and reduced overall survival, suggesting a more general role of the AEP/ATR axis in cancer." (PMID 40012043, 2025). "Given its critical role in allowing cell proliferation in the presence of high levels of genotoxic stress, clinical trials are investigating the efficacy of ATR inhibitors in cancer." (PMID 41190242, 2025). "Until recently, many studies have identified that inhibitors of components in the ATM/ATR/CHK1 pathway in cancers can down-regulate PD-L1 expression and promote the immune microenvironment." (PMID 40740769, 2025). "Radiosensitization, induced by inhibiting ATM, ATR or DNA-PKcs, has been demonstrated in many cancer types." (PMID 40332379, 2025). "We demonstrate that ATR promotes mTORC1 activity across various human cancer cells and both human and mouse normal cells under basal conditions." (PMID 40514450, 2025). "ATR signaling, measured by pChk1-S345 levels, was significantly elevated in cancer cells after PARPi treatment but nearly undetectable in non-transformed hTERT RPE-1 cells." (PMID 40630542, 2025). "This burden can be exploited for cancer treatment by the use of genotoxic drugs that further increase RS and/or by inhibiting the ATR pathway." (PMID 39887032, 2025). "Beyond PARP inhibitors, the ATR inhibitor ceralasertib, combined with the PD‐L1 antibody durvalumab, has shown significant clinical benefits in patients with melanoma and other cancers responsive to immunotherapy." (PMID 40859871, 2025). "Elevated ATR level has been identified as a significant biomarker in several types of cancer, highlighting its potential as a therapeutic target." (PMID 40256842, 2025). "This review discusses the critical roles of Ataxia Telangiectasia Mutated Kinase (ATM), ATM and Rad3-related Kinase (ATR), and DNA-dependent protein kinase (DNA-PK) in the DNA damage response (DDR) and their implications in cancer." (PMID 40256842, 2025). "Other “Tier 1” cancer-related gene mutations in the COSMIC Cancer Gene Census21 present in the 15 most frequently mutated genes include PIK3R1 (4%), NF1 (4%), NOTCH1 (4%), APC (3%), and ATR (3%)." (PMID 40057511, 2025). "These agents heighten RS, making cancer cells increasingly reliant on ATR-mediated RS response pathways for survival." (PMID 40869030, 2025). "Accumulating evidence has shown that ATR inhibition is selectively toxic to cancer cells harboring high levels of RS." (PMID 39875375, 2025). "Since ATR was previously involved in the activation of the DNA damage checkpoint, the protein seems to have two opposite roles in cancer progression." (PMID 39866838, 2025). "While activation of these pathways can induce cell cycle arrest to allow for DNA damage repair, cancers often have other cell cycle or DDR alterations that allow for continued proliferation even in the presence of activated ATR/ATM (Maréchal and Zou, 2013)." (PMID 40514450, 2025). "Our work directly elucidates AEP as a previously unidentified regulator of ATR levels in cancer, thus allowing cancer cells to better cope with genotoxic stress." (PMID 40012043, 2025). "Several small-molecule inhibitors targeting ATM/Chk2 or ATR/Chk1 are currently being tested in preclinical and/or clinical settings, showing promise in cancer models and patients." (PMID 40422251, 2025). "ATR activates mTORC1 by increasing phosphorylation and expression of the de novo cholesterol synthesis enzyme lanosterol synthase in cancer cells." (PMID 40514450, 2025). "This is particularly apparent in cancer, where cells hijack DDR by upregulation of the key DDR proteins Ataxia Telangiectasia and Rad3-related protein (ATR) and/or Ataxia Telangiectasia Mutated (ATM)." (PMID 40514450, 2025). "Together, our data demonstrate an unexpected link between ATR and mTORC1 via cholesterol synthesis in cancer cells." (PMID 40514450, 2025).
cancer (continued). "Chk1 is a DNA repair protein kinase and downstream target of ATR that plays an important role in cancer biology by mediating cell cycle regulation and the DNA damage response." (PMID 40699616, 2025). "ATM is frequently mutated in cancer, and ATM-deficient cancer cells are more sensitive to ATRis, probably because of the interdependence between ATM and ATR in response to secondary DSBs induced by RS." (PMID 39875375, 2025). "Tumor cells’ reliance on ATR signaling due to high replication stress provides a rationale for ATR inhibition as a cancer therapy." (PMID 41417226, 2025). "In preclinical studies, celastrol binds to APE2 and blocks its ssDNA binding and exonuclease functions, thereby impairing ATR–Chk1 signaling in cancer cells." (PMID 41446759, 2025). "Together, these studies provide compelling preclinical evidence that dual targeting of MYC signalling, and ATR-mediated checkpoint control can selectively collapse the replication-stress tolerance of MYC-overexpressing cancers." (PMID 41561634, 2025). "TCGA data analysis revealed that KHSRP expression is associated with the activation of pathways including Activation of ATR In Response To Replication, Transport of Mature mRNAs Derived From Intronless Transcripts, and Signaling by Wnt in Cancer." (PMID 39866240, 2025). "DNA damage activation is found in ATR in tumors and cancer cells, which in turn induces WEE 1 expression, resulting in cell cycle arrest in the G2/M phase." (PMID 40564344, 2025). "The findings indicate that ATR inhibitors plus RT were more potent in cancer cell elimination than RT alone." (PMID 40565309, 2025). "Cancer cells cope with DNA damage and replication stress by upregulating the replication checkpoint response and activation of the kinase ATR and the downstream effector kinase CHK1." (PMID 40615577, 2025). "In response to cisplatin-induced DNA synthesis inhibition and G2/M cell cycle arrest, cancer cells often upregulate ATR as a survival mechanism." (PMID 40940866, 2025). "This review discusses the roles of three major kinases ATM, ATR, and DNA-PK in sensing DNA damage and catalysing DNA repair, as well as their involvement in cancer." (PMID 40256842, 2025). "The activity and functions of ATR are therefore normally crucial for cell viability, mainly in highly proliferative cells including cancer cells, due to generation of replication stress and replication-driven DNA damage." (PMID 39779698, 2025). "ATR plays key roles in cellular responses to DNA damage and replication stress, a pervasive feature of cancer cells." (PMID 39779698, 2025). "Our study redefines the essential role of the 9-1-1 complex in cancer cell survival, uncoupling it from its canonical ATR-checkpoint function and establishing it as a direct protector of ssDNA gaps." (PMID 41278922, 2025). "Its essential role in maintaining genome stability, particularly during replication stress, makes ATR an attractive target for cancer therapy." (PMID 41387887, 2025). "Targeting the ATR/CHK1 axis triggers cancer cell-intrinsic innate immunity via the STING-mediated DNA-sensing pathway, thereby enhancing the therapeutic efficacy of radiotherapy (RT) and ICBs in ARID1A-deficient tumors." (PMID 40750787, 2025). "These cancer cells become highly reliant on stress response pathways such as ATR-mediated checkpoint signaling to survive the R-loop onslaught." (PMID 40332372, 2025). "In HR-deficient cancers, loss of APE1 leads to toxic accumulation of AP sites at replication forks, while loss of APE2 prevents processing of blocked 3′ termini and ATR signaling, causing fork collapse." (PMID 41446759, 2025).